SPINK1 (serine peptidase inhibitor Kazal type 1)
Diseases named in the same sentence as SPINK1 in open-access papers (continued):
Sharing a sentence is not in itself a finding about the gene and the disease.
chronic pancreatitis (continued). "Numerous loss-of-function mutations in the SPINK1 gene are strongly linked to chronic pancreatitis." (PMID 40872585, 2025). "Mutations in the PRSS1 and SPINK1 genes are recognized as important risk factors for chronic pancreatitis (CP); however, their clinical relevance in Vietnamese populations remains unclear." (PMID 40979245, 2025). "SPINK1 (OMIM #167790) stands out as one of the primary genes associated with chronic pancreatitis." (PMID 38414044, 2024). "In this study, we aim to harness the well-established full-length gene splicing assay (FLGSA) in conjunction with SpliceAI to prospectively interpret the splicing effects of all potential coding SNVs within the four-exon SPINK1 gene, a gene associated with chronic pancreatitis." (PMID 38414044, 2024). "In the SPINK1 gene, a mutation is found as a risk factor for chronic pancreatitis." (PMID 36434531, 2022). "Genetic mutations in other types of SPINK such as SPINK1, which is known as a pancreatic secretory trypsin inhibitor, are associated with chronic pancreatitis emphasizing that regulation of pancreatic proteases is an important factor for prevention of pancreatic autodigestion." (PMID 36175575, 2022). "Finally, a better understanding of the digestive mechanism of SPINK1 caused by TRY1 can help to develop a more robust SPINK1 mutant that is hardly digested and can act as a drug for chronic pancreatitis caused by SPINK1." (PMID 34054303, 2021). "Although strongly related, the pathophysiological effect of the N34S mutation in the serine protease inhibitor Kazal type 1 (SPINK1) in chronic pancreatitis is still unknown." (PMID 34054303, 2021). "The loss-of-function mutations of serine protease inhibitor, Kazal type 1 (SPINK1) gene are associated with human chronic pancreatitis, but the underlying mechanisms remain unknown." (PMID 27845447, 2016). "The studies conducted to date suggest that the spectrum of mutations in SPINK1 is geographically varied: the IVS 3 + 2 T > C mutation is more frequent in Chinese children with Idiopathic chronic pancreatitis (ICP), whereas p.N34S is more frequent among western populations." (PMID 26100556, 2015). "Finally, it should be appreciated that an accurate determination of the pathogenic relevance of any SPINK1 intronic variant in chronic pancreatitis is not only important from a mechanistic viewpoint but also provides potential therapeutic targets as shown in other genes." (PMID 30755276, 2019). "Crucially, chronic pancreatitis is an established precursor for pancreatic ductal adenocarcinoma, suggesting a molecular relationship between SPINK1 malfunction, chronic inflammation, and cancer formation." (PMID 40872585, 2025). "After the acute episode, Spink1-KOhet mice developed progressive disease with chronic pancreatitis-like features, whereas C57BL/6N mice recovered rapidly." (PMID 38768901, 2024). "We investigated severity of acute pancreatitis and progression to chronic pancreatitis in Spink1-KOhet mice after transient (10 injections) and prolonged (2 × 8 injections) cerulein hyperstimulation." (PMID 38768901, 2024). "Remarkably, this preservation of 10% residual function correlates with the less severe phenotypes observed in SPINK1 c.194 + 2 T > C homozygotes, who exhibit chronic pancreatitis with variable expressivity." (PMID 38414044, 2024). "There are also genetic (including hereditary chronic pancreatitis due to mutation of the PRSS1 gene but also other forms due to mutations of other genes such as CFTR, SPINK1, TRPV6, and CTRC) and idiopathic forms." (PMID 36765725, 2023).
chronic pancreatitis (continued). "The aim of the study was to determine the structure of chronic pancreatitis genetic causes in patients living in the European part of Russia by sequencing the entire coding sequence of the PRSS1, SPINK1, CTRC, CFTR, and CPA1 genes." (PMID 37389024, 2023). "Recurrent variants of the PRSS1, SPINK1, CTRC, CFTR, and CPA1 genes, contributing to the genetic predisposition to chronic pancreatitis development were identified in a cohort of Russian patients." (PMID 37389024, 2023). "Hereditary pancreatitis refers to acute recurrent or chronic pancreatitis caused by autosomal dominant variants in the PRSS1 gene (serine protease 1), SPINK1 (serine protease inhibitor kazal type 1), or other genes." (PMID 35163129, 2022). "For reported variants in the PRSS1, SPINK1 and CTRC genes, the reader is referred to the Genetic Risk Factors in Chronic Pancreatitis Database." (PMID 35974416, 2022). "Several mutations in the SPINK1 gene are associated with acute recurrent pancreatitis (ARP) and chronic pancreatitis (CP)." (PMID 35408828, 2022). "In the Genetic Risk Factors in Chronic Pancreatitis Database, variants in the PRSS1 and SPINK1 genes are systematically classified in accordance with the ACMG recommended five categories with the addition of a new “protective” category." (PMID 35974416, 2022). "Of the 25 patients, 18 (72%) of them were found to have a known genetic mutation (PRSS1, SPINK1, CFTR, CTRC) as the etiology for acute recurrent or chronic pancreatitis." (PMID 33925523, 2021). "SPINK1 possesses structural similarities to EGF, and is associated with inflammatory states and various cancers, such as chronic pancreatitis, inflammatory bowel disease and colon cancer." (PMID 33015026, 2020). "Rare pathogenic variants in the SPINK1, PRSS1, CTRC, and CFTR genes have been strongly associated with a risk of developing chronic pancreatitis (CP)." (PMID 30420730, 2018). "SPINK1 (encoding pancreatic secretory trypsin inhibitor; OMIM #167790) is one of the most studied genes predisposing to chronic pancreatitis." (PMID 28994706, 2017). "Hereditary pancreatitis is a rare cause of chronic pancreatitis, with mutations in PRSS1, SPINK1, and CFTR genes being the most common genetic causes." (PMID 29515728, 2017). "The Spink3−/−;XXSPINK1 mice, in which this method has been applied to partially restore SPINK1 function, present a novel genetic model of chronic pancreatitis." (PMID 27845447, 2016). "Mutations in genes encoding cationic trypsinogen (PRSS1), pancreatic secretory trypsin inhibitor (SPINK1) and chymotrypsinogen C (CTRC) are associated with chronic pancreatitis." (PMID 24260417, 2013). "In conclusion, the PRSS1 mutations appear capable of inducing chronic pancreatitis whereas CFTR and SPINK-1 seem to be “gene modifiers” capable of inducing the disease in the presence of a risk factor such as alcohol." (PMID 20049222, 2009). "Another gene examined in studying of chronic pancreatitis is the pancreatic secretory trypsin inhibitor (SPINK1)." (PMID 20049222, 2009). "The developed genetic panel (PRSS1, SPINK1, CTRC, CFTR, and CPA1 genes) for identification of genetic risk factors of the chronic pancreatitis development and the usage of the next-generation sequencing technology allowed to specify genetic predictors of the disease development in 61% of patients." (PMID 37389024, 2023). "A sequencing study from China30 explored the germline variation of patients with idiopathic chronic pancreatitis, showing that the SPINK1 c.194 + 2T>C variation was present in 56.2% of adolescent and 42.0% of adult patients with idiopathic chronic pancreatitis." (PMID 35171259, 2022). "Of patients diagnosed with acute pancreatitis, 3.1% also carried the SPINK1 c.194 + 2T>C variation, which suggests that in some patients, a new diagnosis of acute pancreatitis might need to be distinguished from idiopathic chronic pancreatitis." (PMID 35171259, 2022).
chronic pancreatitis (continued). "The mutation also does not result in a misfolding or a complete absence of SPINK1, as this mutation alone is not enough to develop chronic pancreatitis and the mutation is also present in the healthy population." (PMID 34054303, 2021). "Bertin has recently shown that mutations in the cystic fibrosis transmembrane conductance regulator gene (CFTR), the serine protease inhibitor Kazal type 1 gene (SPINK1), and the cationic trypsinogen gene (PRSS1) are associated with both chronic pancreatitis and acute recurrent pancreatitis." (PMID 33319053, 2020). "SPINK1 (serine protease inhibitor, kazal-type, 1; OMIM #167790), which encodes pancreatic secretory trypsin inhibitor, is one of the most extensively studied genes underlying chronic pancreatitis." (PMID 28472998, 2017). "On the other hand, a major proportion of familial chronic pancreatitis that is not autosomal dominant is associated with multiple family members with homozygous SPINK1 mutations." (PMID 18414673, 2008). "In the last decade, several authors identified associations of chronic pancreatitis (idiopathic and hereditary) to other genes, such as the anionic trypsinogen (PRSS2), the Serine Protease Inhibitor, Kazal type 1 (SPINK1) and the cystic fibrosis transmembrane conductance regulator (CFTR)." (PMID 17204147, 2007). "Other genes, such as the anionic trypsinogen (PRSS2), the serine protease inhibitor, Kazal type 1 (SPINK1) and the cystic fibrosis transmembrane conductance regulator (CFTR) have been found to be associated with chronic pancreatitis (idiopathic and hereditary) as well." (PMID 17204147, 2007). "Of note, only 2 of the 21 patients (9.5%) had a history of chronic pancreatitis, suggesting that a SPINK1 variation might be directly associated with pancreatic cancer and not necessarily associated with chronic pancreatitis." (PMID 35171259, 2022). "Other commonly identified genes whose mutations are associated with chronic pancreatitis include the cationic trypsinogen gene (PRSS1) and Cystic Fibrosis Transmembrane Conductance Regulator gene (CFTR), with the later gene being the most common genetic variant to co-exist with SPINK1 mutations." (PMID 29515728, 2017). "We crossed Spink1-KOhet mice with T7D23A and T7D22N,K24R mice that carry strongly autoactivating trypsinogen mutants and exhibit spontaneous chronic pancreatitis." (PMID 38768901, 2024). "It should, however, be noted that in cases where mutations in the SPINK1 and CASR genes or SPINK1 and CFTR genes are co-inherited, chronic pancreatitis can ensue." (PMID 23820649, 2013). "This study demonstrated that three genes, IGFBP3, SPINK1 and PSCA, can differentiate, in tissue samples, cancerous samples from benign samples (normal and chronic pancreatitis cases)." (PMID 21245863, 2011). "Given that in the pancreas, PRSS1, SPINK1 and CTRC are expressed exclusively in the acinar cells, these genetic findings suggested an important role for prematurely activated trypsinogen within the pancreatic acini in initiating chronic pancreatitis." (PMID 23951356, 2013). "The causes of chronic pancreatitis in the patient population of this study were: CFTR and SPINK-1 mutation, non-cancer related obstructive pancreatitis, autoimmune pancreatitis, paraduodenal pancreatitis, hypertriglyceridemia, pancreas divisum morphology, and idiopathic." (PMID 37443666, 2023). "Furthermore, the differential expression patterns of SPINK1, PSCA and IGFBP3 may be of value in the differentiation of pancreatic cancer from chronic pancreatitis." (PMID 21245863, 2011).
prostate carcinoma (58 papers, 2003 to 2025). A carcinoma that arises from epithelial cells of the prostate gland. "In a SPINK1-positive prostate cancer mouse model, cancer-associated mortalities were confirmed and miRNA-338-5p/-421 abrogated oncogenic effects including cell-cycle progression, stemness, metastasis and drug resistance." (PMID 36053457, 2022). "In primary prostate cancer, the SPINK1+/ERG+ phenotype was shown to be associated with a higher Gleason grade and aggressive subpopulation with a higher risk of lymph node metastases." (PMID 33916984, 2021). "Collectively, our findings draw attention towards the widespread use of AR antagonists and the plausible emergence of a distinct resistance mechanism associated with ADT-induced SPINK1 upregulation in prostate cancer." (PMID 31959826, 2020). "In patient studies on breast and prostate cancers, high levels of SPINK1 staining in tumor tissue have been similarly associated with poor prognosis in specific patient subsets." (PMID 26437224, 2015). "On the other hand, we found that high SPINK1 protein expression was associated with lower rates of recurrence after surgery, although SPINK1 overexpression defines only a small subset of prostate cancers (3.4%)." (PMID 26172920, 2015). "While ERG and SPINK1 appear to identify discrete molecular subtypes of prostate cancer, only high expression of SPINK1 was associated with improved clinical outcome." (PMID 26172920, 2015). "In patient 1, SPINK1 was identified in all 3 CTCs analyzed, and accumulating evidence suggests this defines a subtype of prostate cancer that is susceptible to therapies targeting SPINK1 or EGFR (cetuximab)." (PMID 23145101, 2012). "Loss of SPINK1 attenuates invasiveness and tumor growth as has been noted in prostate cancer." (PMID 36053457, 2022). "Moreover, overexpression of SPINK1 is associated with adverse prognosis in other cancers, including prostate cancer, hepatocellular cancer and breast cancer." (PMID 31888570, 2019). "Two established molecular subtypes are identified by high expression of the ERG oncoprotein, due to structural DNA alterations that encode for fusion transcripts in approximately 1⁄2 of prostate cancers, and over-expression of SPINK1, which is purportedly found only in ERG-negative tumors." (PMID 26172920, 2015). "In prostate cancer, urinary SPINK1 levels increase with advancing Gleason score, pathological T stage, and metastatic status, demonstrating significant predictive value for patient prognosis." (PMID 40904507, 2025). "The PCa_GI signature was previously defined and derived from correlation with SPINK1 in primary prostate cancer." (PMID 40553565, 2025). "SPINK1 has also demonstrated tumor growth suppression in colorectal cancer and prostate cancer murine models." (PMID 40904507, 2025). "SPINK1 has been found to stimulate cell proliferation and contributes to prostate cancer cell plasticity through its interaction with the epidermal growth factor receptor." (PMID 38173042, 2024). "Prostate cancer organoids retain parental genetic features, including TMPRSS2–ERG fusion, SPOP mutation, SPINK1 overexpression, and CHD1 loss." (PMID 39309690, 2024). "The top three overexpressed genes whose differential expression was associated with prostate cancer are PCA3, SPINK1, and AMACR, which encode prostate cancer antigen 3, serine protease inhibitor Kazal-type 1, alpha-methylacyl-CoA racemase." (PMID 38173042, 2024). "miR-421 was found to participate in the ADT resistance, Enzalutamide resistance, and Kazal type-1 (SPINK1)-positive prostate cancer, the second most recurring and aggressive subtype of prostate cancer." (PMID 36840946, 2023). "SPINK1, which is highly expressed in prostate cancer, is transcriptionally inhibited by AR and its corepressor, REST, while AR antagonists alleviate this inhibition and lead to upregulation of SPINK1." (PMID 35223512, 2022).
prostate carcinoma (continued). "In prostate cancer, SPINK1 is also mediated by EGFR and is incidentally related to aggressive disease in patients, so it has been used as a plausible target therapy in prostate cancer." (PMID 36053457, 2022). "They used this model to simulate numerous prostate cancer molecular changes, including but not limited to TMPRSS2-ERG fusion, SPOP mutation, SPINK1 overexpression, and CHD1 loss." (PMID 35813047, 2022). "In a SPINK1-positive prostate cancer xenografted mice study, monoclonal EGFR antibody was administered and showed decrease in tumor burden, indicating interaction with EGFR." (PMID 36053457, 2022). "In prostate cancer, miR-5089-5p suppressed SPINK1 mRNA by binding to its 3’UTR to up-regulate matrix metalloproteases 9 and reversed the effect of proliferation, migration and metastasis in drug-resistant cells." (PMID 36053457, 2022). "In a prostate cancer model, miR-338-5p/miR-421 was epigenetically silenced in SPINK1-positive prostate cancer, and miR-338-5p/miR-421 was characterized as post-transcriptionally regulating SPINK1 via 3′UTR binding." (PMID 33916984, 2021). "Conditioned medium containing SPINK1 promoted prostate cancer PCa cell proliferation, and SPINK1 silencing reversed this phenotype." (PMID 33916984, 2021). "Outlier expression of SPINK1 had been reported in a subset of ETS-negative prostate cancer samples exclusively." (PMID 33634124, 2021). "Androgen deprivation was found to upregulate the expression of SPINK1 in neuroendocrine-transdifferentiated prostate cancer cells." (PMID 33916984, 2021). "The knockdown of SPINK1 in the ETS-negative prostate cancer cell line 22RV1 attenuated invasiveness." (PMID 33916984, 2021). "Later, ERG/SPINK1 immunohistochemistry analyses performed in different foci of prostate cancer samples revealed that ERG and SPINK1 overexpression were mutually exclusive in all tumor foci." (PMID 33634124, 2021). "SPINK1 in the conditioned medium also stimulated prostate cancer cell migration in wound healing and transwell assays." (PMID 33916984, 2021). "Collectively, we have shown the direct role of SOX2 in the transcriptional regulation of SPINK1 in prostate cancer." (PMID 31959826, 2020). "Nevertheless, the majority of advanced-stage prostate cancer patients, including those with SPINK1-positive subtype, are treated with AR-antagonists." (PMID 31959826, 2020). "Taken together, our findings demonstrate that AR signaling negatively regulates SPINK1 expression and draws attention to AR antagonists mediated upregulation of SPINK1 in prostate cancer." (PMID 31959826, 2020). "Conclusively, we also show that elevated SPINK1 levels during NE-transdifferentiation strongly emphasizes the potential role of SPINK1 in governing stemness and cellular plasticity in prostate cancer." (PMID 31959826, 2020). "In contrast, SPINK1 overexpression is higher in AAM prostate cancers (~24%) than in CaM cancers (about 8%)." (PMID 31366128, 2019). "miR-338-5p and miR-421 expression can be repristinated in SPINK1-overexpressing prostate cancers through epigenetic drugs affecting EZH2 expression or through synthetic mimics." (PMID 31366128, 2019). "SPINK1 is overexpressed in approximately 10% of prostate cancers, and SPINK1 overexpression and ERG rearrangement appear to be mutually exclusive." (PMID 29581876, 2018). "Previously, we demonstrated that miR‐338‐5p and miR‐421 exhibit tumor suppressive properties in SPINK1 positive prostate cancer (unpublished data)." (PMID 29460395, 2018). "We elucidated a novel reciprocal regulatory network between miR‐338‐5p/miR‐421 and MALAT1 in SPINK1 positive prostate cancer and a potential therapeutic modality." (PMID 29460395, 2018). "Of note, preclinical studies in a mouse model of SPINK1-driven prostate cancer showed therapeutic benefit from a function-blocking SPINK1 antibody." (PMID 26437224, 2015).